MYCN (MYCN proto-oncogene, bHLH transcription factor)
Diseases named in the same sentence as MYCN in open-access papers (continued):
Sharing a sentence is not in itself a finding about the gene and the disease.
tumor (continued). "Yet, re-transplanted U251-MGmycN/Survivin tumor cells with co-expression of Survivin and mycN still showed significant decreased tumor latency than re-transplanted U251-MGmycN/C tumor cells expressing mycN transgene alone." (PMID 29282022, 2017). "Therefore, INRG classification considering IDRF, histological category, MYCN amplification, grade of tumor differentiation and chromosomal aberrations, was applied in our study and showed a significant difference in high-risk patients with complete surgical resection of the tumor." (PMID 28778185, 2017). "The criteria for classification include stage, age, histology, tumor grade and MYCN gene copy number." (PMID 29259192, 2017). "Tumor sections of UPEN‐RB‐175 (MYCN‐amplified, RB1+/+) stained strongly for pRb and ppRb, while the two MYCN‐amplified RB1+/− stained strongly with pRb antibody, but showed weaker staining of fewer cells with ppRb antibody." (PMID 28211617, 2017). "MYCN copy numbers from plasma-derived cfDNA were consistently lower than the corresponding tumor gDNA from patients 6–10 with MYCN-amplified tumors." (PMID 29156716, 2017). "Deregulated expression of the MYC family of transcription factors, particularly c-MYC and MYCN genes, has been found in many of these neoplasms, and their expression levels are often correlated with poor prognosis." (PMID 28333115, 2017). "Our ddPCR protocol accurately detected the ALK normal diploid status and amplified MYCN status of the xenograft tumor from mouse blood plasma." (PMID 29156716, 2017). "A more homogeneous distribution of both T1 and R2* values was apparent in tumours arising in the Th-ALKF1174L/Th-MYCN mice." (PMID 28787429, 2017). "One possible approach consists of inhibiting the function of key target genes of MYCN involved in tumor-promoting processes." (PMID 28358317, 2017). "We stratified the TIN index by main clinical and biological features and observed that it strongly correlates with the patient's clinical stage, age at diagnosis, 5‐year overall survival, and MYCN (single gene copy versus amplified) status of the tumor." (PMID 28941026, 2017). "Since, tumor T7 had acquired focal high-level gain of MYCN, based on WES data this amplification would have been falsely considered the primary event." (PMID 27126562, 2016). "We performed SNP analysis using Affymetrix Cytoscan HD arrays on 63 samples including constitutional DNA, tumor, bone marrow and relapse samples of 26 patients with confirmed hetMNA by MYCN‐FISH." (PMID 26910568, 2016). "One tumor (case 5) showed MYCN and MYCL amplifications, and a 9q deletion encompassing PTCH1; no chromothripsis was seen in that tumor." (PMID 26857864, 2016). "We screened serum samples from 151 patients with NB for MNA, using real-time quantitative PCR, and compared the results with MYCN status determined using paired tumor samples." (PMID 27513929, 2016). "The association of MYCN and MYCL in this tumor is a striking and unique observation, although isolated MYCL amplifications have been sporadically observed in SHH tumors and MYCN is one of the most frequently amplified genes in SHH tumors." (PMID 26857864, 2016). "The tumor with focal 1q32.1 amplification (T21) also showed focal MYCN-amplification and several additional focal amplifications at 2p with similar copy numbers, indicating co-amplification." (PMID 27126562, 2016). "Tumor masses arising in MYCN-overexpressing zebrafish are histologically, immunohistochemically and ultrastructurally very similar to those arising in humans, supporting the use of this model to investigate NB tumorigenesis." (PMID 27822138, 2016). "Both FDGhi and FDOPAlo phenotypes correlated with higher HK2 expression, which is required for oncogenic transformation in vitro and tumor initiation in vivo and is enhanced by MYCN and HIF-1α." (PMID 26959748, 2016).
tumor (continued). "MYCN amplification was identified as first genetic prognostic marker, in addition to age at diagnosis and tumor stage, which is still used today in therapeutic stratification." (PMID 26646589, 2016). "MYCN-directed treatment by AuroraA- or Brd4-inhibitors resulted in significantly decreased cell proliferation in vitro and reduced tumor growth in vivo." (PMID 27769070, 2016). "The most consistent abnormalities found in this tumor entity include ploidy changes, deletions of chromosome arms, amplification of the MYCN oncogene, and most frequently gains of chromosome arm 17q." (PMID 27064200, 2016). "These include stage, age, histology (i.e. grade of tumor maturation), MYCN gene copy number, status of the long arm of chromosome 11 and DNA ploidy level of the tumor cells." (PMID 27560999, 2016). "NB patients are assigned to three different risk categories according to clinicopathologic variables such as age at diagnosis, MYCN oncogene amplification, tumor histology and DNA ploidy." (PMID 26824183, 2016). "Activated AKT correlated with advanced stage, unfavorable histology, poor outcome, and MYCN amplification in human tumor specimens." (PMID 26771642, 2016). "Our results showed that after 1 week of MycN knockdown, there was significant increase in the expression of well-recognized tumor suppressors that induce G1 cell cycle arrest, such as Cdkn1a, Cdkn2a and Cdkn2b." (PMID 26815535, 2016). "Consistently, we have illustrated that MycN knockdown in human NCSCs increased the expression of Cdkn1a, Cdkn2a and Cdkn2b, emphasizing the critical role of these tumor suppressors in stem cell growth and cell cycle progression." (PMID 26815535, 2016). "Traditionally, the tumor biology of NB has been defined by age, stage, histopathology, MYCN amplification, and ploidy." (PMID 26959748, 2016). "This is supported by the finding that MYCN levels are undetectable or low in target organs in tumor-free animals." (PMID 27769070, 2016). "In order to model the spectrum of MYCN-driven neoplasms in mice, we transgenically overexpressed MYCN under the control of the human GFAP-promoter that, among other targets, drives expression in neural progenitor cells." (PMID 27769070, 2016). "MYCN is able to promote proliferation and repress differentiation, which promotes tumor growth in numerous malignancies." (PMID 27769070, 2016). "In fact, MYCN oncogene amplification, which is observed in 20% of patients with NB, plays a role in tumor progression and aggressiveness." (PMID 27822138, 2016). "There is a general agreement that MYCN gene amplification plays a major role in driving NB tumorigenesis, while ALK gene mutation cooperates with MYCN to enforce tumor aggressiveness." (PMID 27822138, 2016). "Together, our results support an important role of the tumor suppressor nf1 in restricting both the proliferative rate and survival of MYCN-overexpressing hyperplastic sympathetic neuroblast precursors." (PMID 27130733, 2016). "Cinacalcet significantly inhibited tumor growth in MYCN-amplified xenografts and reduced that of MYCN-non amplified PDX." (PMID 26893368, 2016). "We have previously shown that indirect methods of blocking MYCN in these animals have led to decreased tumor size and improved survival." (PMID 26029667, 2015). "Our observation that combining pharmacological concentrations of drugs targeting the MYCN network can activate synthetic lethality in MYCN-amplified tumor cells suggests that this approach has the potential to be successfully translated in the clinic." (PMID 25477524, 2015). "In a next step, we explored how expression levels of miRNAs that target MYCN are dynamically regulated during MYCN-driven tumor formation." (PMID 25294817, 2015). "Similar results were obtained in a MYCN-amplified tumor cell line (NB8) with endogenous α4 expression." (PMID 25973900, 2015).
tumor (continued). "We further show on-target efficacy against tumor MYCN protein, marked decrease in proliferation and increase in tumor apoptosis as well as apparent tumor vascular collapse." (PMID 26029667, 2015). "In our study, 2 patients with MYCN amplification died 3 months after brain metastasis, suggesting that MYCN amplification facilitates tumor growth and metastatic potential." (PMID 26370236, 2015). "We have shown that transient downregulation of MYCN in these mice resulted in tumor cell senescence and improved survival." (PMID 26029667, 2015). "Tumor stage, age at diagnosis, tumor histology, MYCN amplification (MNA), and ploidy are the main prognostic factors for NB patients." (PMID 25595889, 2015). "In a next step, we investigated the dynamic regulation of these miRNAs during the process of MYCN-driven tumor formation, using the extensively validated TH-MYCN mouse model." (PMID 25294817, 2015). "We regarded tumour specimens that scored positive for MYCN amplification as a separate group of tumours." (PMID 25266063, 2015). "In a SNP array analysis of a bilateral case, a relatively focal single copy gain of MYCN was detected in both contralateral tumours." (PMID 25749049, 2015). "Other Aurora A inhibitors also decreased N-Myc expression resulting in inhibited tumor growth of other MYCN-amplified tumors." (PMID 26380220, 2015). "Copy number gains that included the MYCN locus were detected in 37/292 (12.7%) of tumours overall, and in 7/23 (30.4%) of diffuse anaplastic WTs." (PMID 25749049, 2015). "PW-12 treated tumors demonstrate a significant decrease in MYCN protein expression and in tumor mass (p < 0.05) when compared to vehicle treated controls, consistent with direct blockade of MYCN and subsequent anti-tumor effects." (PMID 26029667, 2015). "To better understand the role of MYCN in MB in vitro and in vivo and to aid the development of MYCN-targeted therapeutics we established tumor-derived neurosphere cell lines from the GTML (Glt1-tTA/TRE-MYCN-Luc) genetically engineered mouse model." (PMID 25785590, 2015). "We reasoned that the expression of a targeting miRNA is inversely correlated to MYCN mRNA expression levels or MYCN activity in primary tumor samples." (PMID 25294817, 2015). "While MYCN expression in development and neoplasia inhibits neural differentiation to maintain cells in a precursor state, our results indicate that MYCN strongly promotes the neural lineage in multipotent SAPs." (PMID 26222553, 2015). "We therefore examined these data to determine if there is evidence of significant differential regulation of MYCN expression in this tumour series." (PMID 25749049, 2015). "The MYCN crucial role in the control of tumor initiating cell development is further demonstrated by data obtained modulating MYCN expression through miR-mediated regulation." (PMID 26439802, 2015). "The long delay between initiation of MYCN expression and tumor generation in that mouse model also supports the concept that additional genetic mutations are necessary." (PMID 26222553, 2015). "This study included metastatic patients over 1 year of age and patients with localized MYCN-amplified tumor." (PMID 25886486, 2015). "We therefore planned to identify, at the global level, the genes interacting functionally with MYCN required to promote fitness of tumor cells facing oncogenic stress." (PMID 25477524, 2015). "Given that MYCN overexpression imparts tumor-like features including enhanced proliferation, neural lineage commitment, and colony forming potential, we assessed the ability of MYCN overexpressing adrenal progenitor cells to form tumors in vivo." (PMID 26222553, 2015).
tumor (continued). "Nevertheless, both cdk1 expression and CCNB1 expression were significantly higher in MYCN-amplified tumor." (PMID 26029996, 2015). "The clinical course varies from spontaneous tumor regression to an aggressive, poorly responding disease, depending on patient age at diagnosis, metastatic dissemination and MYCN status." (PMID 25886486, 2015). "This MYCN signature score increases significantly throughout tumor progression from tumor-prone ganglia to tumors in transgenic mice, compared to wild-type ganglia." (PMID 25294817, 2015). "Local relapse was observed in 7 out of 19 (37%) patients with MYCN-amplified tumor, while relapses were recorded in only 5 out of 37 (14%) patients with non-MYCN-amplified tumors (P < 0.005)." (PMID 25886486, 2015). "Taken together, these results suggest that MYCN acts to clonally expand highly proliferative tumor-propagating cell in GTML neurospheres resembling a stem and/or progenitor-like cell marked by CD133 positivity." (PMID 25785590, 2015). "It has also been shown that expression of MYCN can induce tumor formation in the zebrafish interrenal gland, the equivalent of the mammalian adrenal gland." (PMID 26222553, 2015). "Our data therefore suggest that MED1 is derived from a large cell anaplastic Group 4 tumour with MYCN amplification." (PMID 24887326, 2014). "Ultrastructural morphological examination demonstrated that MYCN amplified tumours had a subjectively ‘less differentiated’ ultrastructural appearance, with scanty neuritic processes, which contained fewer NSG and NT." (PMID 24679140, 2014). "On the other hand, clinical features of patients whose tumours harbour regional amplifications other than MYCN together with MNA are comparable to those with MNA only." (PMID 25013904, 2014). "To date, only E2F1 and MYCN have been shown to be direct activators of Bmi1 transcription in some kinds of cancers, and data regarding Bmi1 in tumor biology are far from complete." (PMID 24559156, 2014). "Another approach is to dissect the signaling pathways that lie downstream and upstream of MYCN, trying to illuminate the gene networks required for homeostasis of tumor cells with deregulated MYCN." (PMID 26029658, 2014). "However, among patients with MYCN-amplified low-stage NB, the outcome was significantly better for patients with hyperdiploid tumors when compared to those with diploid tumors, suggesting that tumor-cell ploidy could potentially improve risk classification." (PMID 24904828, 2014). "The non-MYCN amplified tumours had a more differentiated ultrastructural appearance, with frequent cell processes all appearing well developed with abundant NSG and NT." (PMID 24679140, 2014). "We employed ELDA (extreme limiting dilution analysis) to evaluate the sphere-forming potential of both tumor cells freshly prepared from tumors of MYCN hemizygous transgenic mice and tumorsphere cells passaged 4 times in #4 medium." (PMID 24466252, 2014). "Using vandetanib, we show that RET inhibition strongly impairs tumor growth in vivo in both MYCN/KI AlkR1279Q and MYCN/KI AlkF1178L mice." (PMID 24811913, 2014). "In a recent study, we suggested that the high expression of MYC/MYCN is critical to the existence of stem cell-like tumor-initiating NB cells." (PMID 24190252, 2014). "Here, we show that by microarray and IPA analysis in NB tumor samples, the regulation of MYCN expression is closely related to AHR expression." (PMID 24586395, 2014). "This is linked to poor survival outcome due to the complex conditions of two important prognostic determinants: loss of tumor suppressors (chromosome 17p) and high expression of oncogenes c-myc (MYCC) or N-myc (MYCN)." (PMID 24502646, 2014).
tumor (continued). "While the MYCN protein is established as an important regulator of several miRNAs involved in NB tumorigenesis, tumor suppressor miRNAs have also been documented to repress MYCN expression and inhibit cell proliferation of MYCN-amplified NB cells." (PMID 24806581, 2014). "In NB, a pediatric cancer of the sympathetic nervous system, MYCN-amplification is strongly correlated with poor prognosis and advanced tumor stage, and these tumors are often resistant to multimodal therapy." (PMID 24859015, 2014). "Previous evidence have shown that MYCN amplification is one of the critical aspects in tumor progression and poor prognosis in NB, and MYCN is often considered an attractive target for therapeutic intervention strategies in this malignancy." (PMID 25033461, 2014). "NVP-BEZ235 is a dual inhibitor of both PI3K and mTOR and promotes the degradation of MYCN to effectively reduce tumor burden in the MYCN transgenic mouse via GSK3β activation." (PMID 24391509, 2014). "We previously established an allograft tumor model by serially allografting minced tumors of MYCN Tg mice." (PMID 24466252, 2014). "The Children Oncology Group resolved these criteria through “The Risk Stratification System” that incorporates the patient age at diagnosis and INSS stage as well as tumour histopathology, DNA index, and MYCN gene status." (PMID 25548681, 2014). "Over the past three decades, tumor histology, status of the MYCN oncogene, and tumor cell DNA content (ploidy) have each been shown to be independently predictive of patient outcome in large retrospective and prospective studies." (PMID 25161957, 2014). "Several putative tumor suppressors have been identified as MYCN-repressed genes, including p75, TRKA, CASZ1, and clusterin." (PMID 26029658, 2014). "MYC amplifications were essentially restricted to Group 3 (only one out of 8 patients had Group 4 tumor), and MYCN amplifications to SHH and Group 4 tumors." (PMID 24791927, 2014). "On the other hand, miRNAs with tumor suppressor functions (mir-184 and mir-542-5p) have been shown to be inversely correlated to MYCN expression." (PMID 24806581, 2014). "Non-MYCN amplified tumours show increased features of neuronal differentiation, with fewer neurosecretory granules (NSG) and NT in the cytoplasm." (PMID 24679140, 2014). "MYCN amplified tumours generally exhibited a ‘less differentiated’ ultrastructural phenotype, with significantly smaller neurotubules (NT) in the cell body (p < 0.002)." (PMID 24679140, 2014). "The pro-survival effects of BMI1 suggest MYCN induction leads to greater chances for tumor initiating events." (PMID 23373009, 2013). "Here, we add further evidence for selective advantage for tumor cells exhibiting focal gains and losses encompassing genes under direct or indirect transcriptional control of MYCN." (PMID 23308108, 2013). "In NB tumor samples, within the MYCN gene signature set, 30% of the down-regulated genes in the set are neuronal tissue-specific genes while only 2% of such genes are up-regulated." (PMID 23373009, 2013). "MYCN protein expression was inhibited about 60% in vivo, thus induced tumor cell apoptosis markedly." (PMID 23806172, 2013). "Amplification of MYCN oncogene is an established marker indicating aggressive tumor progression of NBL." (PMID 23320395, 2013). "This indicates that folate-nanoliposome entrapped MYCN siRNA is specifically distributed in tumor tissues." (PMID 23806172, 2013). "NB patients over 18 months of age at the time of diagnosis are often in the later stages of the disease, present with widespread dissemination, and often possess MYCN tumor gene amplification." (PMID 23440295, 2013). "Array-CGH showed slight elevation of the log2 ratio between the blood and the tumor and three independent qPCR experiments targeting each of the MYCN exons further confirmed MYCN gain." (PMID 24131700, 2013).